CD4 (CD4 molecule)
Diseases named in the same sentence as CD4 in open-access papers (continued):
Sharing a sentence is not in itself a finding about the gene and the disease.
tumor (continued). "Additional analysis of tumour-infiltrating Ifngr1−/− T cells revealed a significantly higher proportion of Treg in CD4+ T cells, reduced ratios of CD4+ non-Treg/Treg and CD8+/Treg cells, and decreased CD4+IFN-γ+ TILs, as compared to tumour-infiltrating WT T cells." (PMID 27498556, 2016). "In contrast, BCL1 tumor cells, whether dormant or active, had no inhibitory effects on CD4+ T cells in the spleen." (PMID 27959896, 2016). "TIM-3 upregulation was only detected specifically in T cells from tumour-bearing lungs but not mediastinal lymph node, peripheral blood or spleen (data not shown) and was predominantly found on anti-PD-1 antibody bound CD4 and CD8 T cells." (PMID 26883990, 2016). "Immunological analysis indicates that, compared with those tumours from the no-treatment group, tumour tissues isolated from mice treated with PEG2k-Fmoc-NLG(L) are more immunoactive with more functional CD4+ and CD8+ T cells, decreased Treg and MDSC, and increased M1/M2 ratios." (PMID 27819653, 2016). "DC-derived MHC class II molecules and tumor-derived antigenic peptides travel by separate routes and converge to form MHC class II-peptide complexes in DC-tumor FCs, where MHC class II-antigenic peptide complexes are expressed on the DC-tumor FC surface and presented to CD4+ T cells." (PMID 27240347, 2016). "In addition, it remains to be seen whether CD4+ T cells inducibly produce MCSF in sterile disease settings, such as tumor microenvironments, in which macrophages and other myeloid cells play important roles." (PMID 27923070, 2016). "Therefore, PD‐1 expression on the surface of peripheral blood CD4+ T cells is not consistent with the expression observed from tumor microenvironments in individual patients." (PMID 27709793, 2016). "On the other hand, type 2 CD4+ T-helper cells (Th2), including Forkhead box P3 (FOXP3) CD4+ regulatory T-cells, inhibit CTL function, support proliferation of B-lymphocytes, and may promote an anti-inflammatory immune response that could enhance tumor growth." (PMID 27777769, 2016). "This association was also specifically observed when the density of CD8+ and CD4+ in the tumor was low, but not in other cases, suggesting the importance of assessing the relative proportion of conventional and regulatory T cells present in the tumor surroundings." (PMID 27463005, 2016). "Indeed, we found that the administration of LPS enhanced tumor destruction only in non-irradiated mice that were depleted of host CD4+ T cells (PFI + anti-CD4 + LPS > PFI + LPS or PFI + anti-CD4)." (PMID 26885368, 2016). "Using major leukocyte lineage markers (CD3, CD4, CD8, CD66b, CD33, CD19, and CD56) we were able to determine using Ward’s minimum variance algorithm that leukocyte abundances and phenotypes determined from FNA samples largely are representative of the whole tumor." (PMID 27539742, 2016). "MICA shedding not only results in a reduction of MICA surface density on tumor cells but also generates sMICA, which was shown to systemically down-regulate NKG2D on cytotoxic effector cells and to promote expansion of immunosuppressive, intratumoral CD4+ NKG2D+ T cells." (PMID 27306684, 2016). "The increase in ICOS on CD4+ T cells was most prominent within the tumor/lungs, but elevated levels were also detected in the periphery of the treated groups but not in the control, tumor-bearing mice." (PMID 26961085, 2016). "Therefore, ICOS expression was induced on CD4+ T cells by the presence of the tumor without any treatment." (PMID 26961085, 2016). "With Foxp3 as the marker, CD4+ helper T cells could be classified into effective T cells that are helpful to promote immune responses (CD3+CD4+Foxp3-), as well as regulatory T cells (Tregs) (CD3+CD4+Foxp3+) which could hamper effective anti-tumour immune responses." (PMID 27767031, 2016).
tumor (continued). "Furthermore we have previously found that inducing expression of CIITA in PELs, which consequently upregulates surface class II expression, allows recognition by KSHV-specific CD4+ T cells but not killing of these tumor cells." (PMID 27893813, 2016). "As expected, tumor-derived TGF-β1 established a systemic immunosuppressive environment that was represented by an increase of the CD4+Gr11b+ T-cell population and a decrease of the activated subpopulation of CD4+CD44+CD62L– T cells in lungs and spleens and CD8+IFNγ+ T cells in spleens." (PMID 27036297, 2016). "However, the treatment effects of tumor reduction and prolonged survival were observed in CD4 depleted, E7 long peptide vaccinated mice compared to mice without CD4 depletion." (PMID 26949512, 2016). "The expansion of Tregs in CD4+ TILs might contribute to the immune evasion of SCCs via multiple mechanisms, because Tregs can inhibit CD8+ T cell-mediated tumor killing, directly kill antigen presenting cells or secrete a number of inhibitory factors which have immune suppressive effects." (PMID 27835902, 2016). "Like CD8+ T cells, we found that L-selectin was strongly downregulated on CD4+ T cells of tumor-bearing mice regardless of whether there was an intact splenic microenvironment." (PMID 27929373, 2016). "In addition, iTregs did not appear to control the effectiveness of CD4+ T cell tumor clearance, which was independent of iTreg number." (PMID 27121060, 2016). "In addition, vaccine did not significantly alter levels of tumor-infiltrating CD25 + Foxp3+ regulatory CD4+ T-cells (Data not shown)." (PMID 28018602, 2016). "CD4+ T cells might directly affect tumor growth via MHC class II or in MHC class II negative tumors CD4+ T cells might provide T cell help to CTL." (PMID 27060000, 2016). "However, the study showed an influx of tumoricidal macrophages and tumor regression independent of CD4 of CD8 T cells." (PMID 27472363, 2016). "We did not observe CD4+ T cell infiltration into the tumor lesions (data not shown)." (PMID 26928306, 2016). "Additionally, tumor-infiltrated neutrophils expressed higher levels of MPO and Fas/FasL, which may be involved in TAN-mediated inhibition of CD4+ and CD8+ T cells." (PMID 27446967, 2016). "Immune reconstitution slowed but could not eliminate tumor growth and this effect required the presence of CD4+ T cell help." (PMID 25901284, 2015). "Curcumin mediates several processes like restoration of CD4+/CD8+ T cell populations, reversal of type-2 cytokine bias, reduction of Treg cell population and suppression of T cell apoptosis; all these help to resurrect tumor immune surveillance that leads to tumor regression." (PMID 26464579, 2015). "In addition, NSG animals that had been reconstituted with CD4-depleted PBL failed to control tumor growth." (PMID 25901284, 2015). "In particular, the role of CD40 in generating T cell responses provides the possibility of eliciting effective anti-tumor immune responses because CD40 on APC can deliver co-stimulatory signaling for the activation of CD8+ cells directly without the activation of CD4+ helper T cells." (PMID 25992978, 2015). "As such, while CD4+ cells may be important we cannot rule out a significant contribution of the CD8+ T-em population with respect to controlling tumor growth." (PMID 25901284, 2015). "Similarly to CD4-cre x IKKβfl/fl mice, enriched CD8+ splenic T cells from tumor-bearing CARMA1-KO mice failed to produce IFN-γ in response to re-stimulation with irradiated tumor cells, indicating a failure to mount a successful anti-tumor effector response." (PMID 25648675, 2015). "However, Tregs from both Loxoribin-treated tumor-bearing mice failed to suppress the CD4+CD25−T cell proliferation." (PMID 25593198, 2015). "In addition to directly reducing CD4+ and CD8+ T cells apoptosis, PD-1 blockade may also restore T cell activity by decreasing the CD47 expression in the tumor microenvironment." (PMID 26573233, 2015).
tumor (continued). "The anti-tumor effect in vivo did not correlate with an increased T cell infiltration since only a few CD4 or CD8 positive cells were observed in the MC38-C215 tumors at end-point without significant differences between control and tasquinimod treated tumors (unpublished observations)." (PMID 26673090, 2015). "Intratumoral CD4+CD25+ Tregs in NHL specimens not only directly inhibited proliferation of autologous infiltrating CD8+ T cells, but also prevented both production and degranulation of perforin and granzyme B, molecules critical to their anti-tumor cytolytic functions." (PMID 25941795, 2015). "Initially, human CD4+ and CD8+ T cells in C4-27z and C4opt-27z CAR cohorts were present in lower numbers in the peripheral circulation in comparison to CD19-27z CAR T cells, suggesting early FRα-specific CAR T cell migration to specific tumor sites (student t test, p < .01 - .001)." (PMID 26359629, 2015). "In comparison, depletion of CD4 T cells did not inhibit tumor regression." (PMID 26337837, 2015). "Nevertheless, the analysis of Treg in several tumor types indicated that FoxP3+ expression may be related to CD4+ T-cell activation rather than to an immune suppressive phenotype." (PMID 26161395, 2015). "However, the proportions of Tregs, CD4+ conventional T cells and CD4− T cells were comparable among each group, suggesting AR knockdown did not alter the recruitment of each T cell subset into the tumor." (PMID 26451607, 2015). "CD4+IL-17+ T cell subset had a similar tend as that of CD4+IFN-γ+ subset in the absolute cell numbers following the tumor development, but its percentage and relative cell numbers maintained relative higher levels in the late cancer stage compared with IFN-γ+CD4+T cells." (PMID 25968569, 2015). "Lack of tumor rejection in CD4-cre x IKKβfl/fl mice may depend on impaired survival, proliferation, differentiation, migration or effector function of tumor-reactive T cells in vivo." (PMID 25648675, 2015). "Interestingly, Helios+ cells were not increased in the CD4 effector population, suggesting that the tumor microenvironment favors the activation and proliferation of Apc/Min+ Treg." (PMID 26146642, 2015). "Interestingly, their deficiency specifically suppresses PD-1 expression in CD8+ effector T cells without affecting CTLA-4 expression or the percentages of tumor-infiltrating CD4+Foxp3+ regulatory T cells (Tregs)." (PMID 25851535, 2015). "Notably, irradiation-induced increases in T-cell viability (as shown for Jurkat cells in vitro) and changes in the proportions of CD3+CD4+CD8− and CD3+CD4−CD8+ T-cells (as shown in vivo) may aid in controlling tumor growth." (PMID 26633364, 2015). "Furthermore, CD4+ T cells have been shown to directly inhibit tumor growth and progression independent of their effects on CD8+ T cells." (PMID 25993655, 2015). "Thus, presence of CD4+ and CD8+ T cells at tumor site is a good prognostic indicator." (PMID 26000310, 2015). "All of this is further complicated by the apparent existence of the two functionally distinct CD4+NKG2D+ T cell subpopulations, which could influence the fate of the anti-tumor immune response, that is, to support cytotoxicity versus immunoregulation or vice versa." (PMID 26486970, 2015). "The mechanisms by which CD4+ T cells mediate tumor rejection are not clear." (PMID 25993655, 2015). "The absence of host CD4+ T cells in lethally irradiated BALB/c mice may thus be another reason why IL‐12/15/18‐preactivated NK cells did not improve survival of tumor‐bearing mice." (PMID 25778912, 2015). "Indeed, Carlson and coworkers recently demonstrated that NB tumor-infiltrating CD4+ T cells can be activated in the tumor milieu, but not in the periphery." (PMID 26161395, 2015). "In addition, these results showed that the selective depletion of effector cells in vivo indicated that CD8+ T cells, but not CD4+ T cells or NK cells, was required for the anti-tumor response." (PMID 26394925, 2015).
tumor (continued). "However, young tumour-specific CD4+ T cells primed in aged mice did not mount protective immune responses against tumour." (PMID 25850032, 2015). "The lipid levels of tumor-infiltrating CD8α+CD4- DCs did not vary between small and large tumors." (PMID 25886502, 2015). "Unexpectedly, EBNA1-specific CD4+ T cells had no or a tumor growth-promoting effect in vivo." (PMID 24853673, 2014). "We demonstrated that Granzyme B-generating CD4+ and CD8+ T cells were significantly enhanced in mice that were immunized with scFv-MTBHsp70-bound tumor cells, as compared to those in the mice immunized with tumor cells alone, MTBHsp70-bound tumor cells, or saline." (PMID 24565018, 2014). "However, there was no significant change in the CD4+CD25+FoxP3+ tumor cell population in the local pGmCSF-b7.1 treatment." (PMID 25034887, 2014). "Depletion of CD8 T cells, either alone or in combination with CD4 T cells, completely abrogated any vaccine induced survival benefit, reducing the survival of CD8-depleted groups to that of the surgery only group, indicating that CD8 T cells are essential for an effective anti-tumor immune response." (PMID 25186961, 2014). "Initially named blastic NK/T cell lymphoma or agranular CD4+/CD56+ hematodermic neoplasm/tumour, BPDCN is –according to the current WHO classification- classified as an acute myeloid leukemia-related precursor neoplasm that has been shown to derive from precursors of plasmacytoid dendritic cells." (PMID 25115387, 2014). "Taken together, our observations of high proportions of CD4+CD25+FoxP3+ Tregs in tumors and CD8+ T cell recruitment blockage strongly support the possibility that these Tregs may inhibit local antitumor immunity at the tumor site." (PMID 24637664, 2014). "Increasing evidence suggests that both CD4+ and CD8+ T cells play a critical role in cancer immunosurveillance and anti-tumor immunity, and manipulation of these immune cells to recognize and eradicate tumor cells is a promising strategy for treating patients with invasive and metastatic cancers." (PMID 25231413, 2014). "Here, we will focus on the anti-tumor properties of CD4+ T cells in the absence of CD8+ T cells." (PMID 24782871, 2014). "Furthermore, the MDSC accumulation was elevated after chemo-immunotherapy in both mouse spleens and tumors; this accumulation had a positive correlation with tumor growth and simultaneously a negative correlation with the amount of CD4+ cells." (PMID 24608924, 2014). "The number of activated (CD25+ CD62Llow) and IFNγ-producing OTII CD4 T cells was significantly greater in the 12-month-old CR mice than 12-month-old ad libitum mice (AL-LRD) and was comparable with young 2-month-old mice (2MO), verifying the findings from the tumor setting." (PMID 24682539, 2014). "Because Th1 response was mainly induce by CD8+ and CD4+ T cells as well as NK cells and the CD8+ CTLs play a major role in anti-viral and anti-tumor responses, we further investigated to determine whether these two candidate peptides induce CD8+ CTL response using flow cytometry analysis." (PMID 25141788, 2014). "To further characterize the immunologic mechanisms behind the anti-tumor effects of IL-2-based immunotherapy and the role of CD4+ T cells in antigen non-specific bystander expansion, we analyzed the phenotype and function of the proliferating CD8+ cells after IT in the absence of CD4+ T cells." (PMID 25119341, 2014). "In addition, the relative numbers of CD4+CD25+Foxp3+ Tregs and CD8+ T cells were negatively correlated in the tissue of PDA patients, and the abundance of Tregs was significantly correlated with tumor differentiation." (PMID 24637664, 2014). "However, four weeks after treatment with CY, we did not observe a significant reduction of Tregs in tumor infiltrating CD4 cells." (PMID 24416401, 2014).
tumor (continued). "We found significantly higher numbers of infiltrating CD4+ T cells in the brains of mice treated with the combination of anti-4-1BB and anti-CTLA-4 antibodies as well as the mice treated with triple therapy when compared to brains of non-tumor bearing mice (p<0.05)." (PMID 25013914, 2014). "Additionally, CD4-depleted mice treated with CRTE6E7L2 DNA vaccine had significantly lower lung weight compared to untreated tumor-bearing mice with or without CD4 depletion." (PMID 24594273, 2014). "Moreover, studies done in an MHC class I-restricted T cell receptor (TCR) transgenic mouse showed that CD8+ T cells, in the absence of CD4+ T cells, maintained their anti-tumor effect." (PMID 24782871, 2014). "Lymphocyte subset depletion experiments demonstrated that tumor protection by anti-PD-1/OX40 mAbs was dependent on the CD4+ and CD8+ T cells as removal of CD4+ or CD8+ T cells but not NK cells completely abrogated the antitumor effect conferred by anti-PD-1/OX40 mAb treatment." (PMID 24586709, 2014). "CD4+ T cells were co-cultured with tumor cells (MCF7, PC3 or M628) pretreated with or without Poly-G3, and the expression of cell cycle molecules and the suppressive effects on T-cell proliferation were determined using Western blot and [3H]-thymidine incorporation assays, respectively." (PMID 25231413, 2014). "Therefore, we hypothesized that CD4+IL-17+ Th17 cells might be a key link between CD4+CD25+Foxp3+Tregs and tumor growth and metastasis." (PMID 24949077, 2014). "In addition, CR fully sustained antigen-specific CD4 T cell priming in aged hosts (12 months old), whereas tumor-specific CD8 T cell priming was not fully maintained compared to young reference animals (2 months old)." (PMID 24682539, 2014). "Collectively, these results indicate that the primary anti-tumor response of naïve CD4+ T cells is followed by T cell differentiation into Th1 (or possibly Th17) cells that confer anti-tumor immunity irrespective of MHC class II expression on tumor cells." (PMID 24782871, 2014). "Exploring the interaction between CD4+CD25+Foxp3+Treg and CD4+IL-17+ Th17 cells has great implications for understanding regulation of the immune inflammatory microenvironment and for the clinical application of traditional Chinese medicine in the reversion of tumor growth and tumor immune escape." (PMID 24949077, 2014). "CD4+ T cells contribute to tumor eradication, even in the absence of CD8+ T cells." (PMID 24782871, 2014). "In addition, a significant down-regulation of CD28 was induced in naïve CD4+ T cells after co-culture with the different types of tumor cell lines but not with normal breast cells." (PMID 25231413, 2014). "While there remains controversy concerning whether development of CD4 or CD8 immunity will best predict host-resistance, there is also concern that vaccination may augment induction of Tregs to block effective tumor immunity." (PMID 25409195, 2014). "Topical administration in the mice depleted CD4+ T and CD8+ T cells in the peripheral blood circulation, redistributed them in mouse CLNs and brain, and reversed tumor immune suppression by significantly reducing the absolute number of Tregs in the tumor microenvironment." (PMID 25411122, 2014). "Strategies that enhance the polyfunctional effector profiles of CD4+ T cells may therefore improve the efficacy of CAR therapy, particularly as it has been established that CAR-engrafted CD4+ T cells play a crucial role in tumour eradication." (PMID 24116999, 2014). "In other MHC IINEG models where tumor cells is reported to be rejected by CD4+ T cells, there is scarce information as to whether tumor-specific antigen is secreted or not." (PMID 24782871, 2014). "For instance, exosomes loaded with tumor antigens have been shown to stimulate CD4+ and CD8 + T cell lmphocytes, and exosomes from in vitro cultured antigen presenting cells (APCs) administrated in vivo can induce T-cell lymphocyte responses resulting in inhibition of tumor growth." (PMID 24912806, 2014).